CD47 (CD47 molecule)
Diseases named in the same sentence as CD47 in open-access papers (continued):
Sharing a sentence is not in itself a finding about the gene and the disease.
tumor (continued). "Thus, it is believed to be important to block CD47–SIRPα interactions removes this inhibitory checkpoint signal augmenting the macrophage-mediated clearance of cancer cells, inducing DCs endocytosis and activation with the consequent T-cell mediated tumor clearance." (PMID 35664746, 2022). "The relationship between CD47 and other tumors was analyzed from four aspects: DNA methyltransferase, TMB, MSI, and tumor cell stemness." (PMID 35433462, 2022). "When anti-CD47 antibodies were used, the overmuch CRT on tumor cells would bind to LRP first, leading to neoplasm preferentially elimination." (PMID 35978433, 2022). "Currently, only PD1/PD-L1, CD47/SIRPα, TIM3/Galectin-9, and CD70/CD27 checkpoints have been shown to interact with each other to regulate tumor proliferation in pairs." (PMID 36358792, 2022). "The data so far show that while CD47 expression varies between SGC subtypes, expression levels are similar between tumor cells and TIICs." (PMID 36171566, 2022). "Researchers demonstrated that combined SIRPα-Fc and CQ treatment interrupted the CD47/SIRPα axis and disrupted the protective autophagy in tumor cells, enhanced phagocytosis of macrophages, and then activated CD8+ T cell-mediated anti-tumor immune." (PMID 36300110, 2022). "SIRPγ bridged MST1 and PP2A to facilitate MST1 dephosphorylation, resulting in Hippo/YAP activation and leading to cytokine release by CSLCs, which stimulated CD47 expression in LUAD cells and consequently inhibited tumor cell phagocytosis." (PMID 35229723, 2022). "In this review, we present the proliferative role of 15 immune checkpoints, including PD1, PD-L1, FGL1, CD155, CD47, SIRPα, CD276, IDO1, SIGLEC-15, TIM3, Galectin-9, CD70, CD27, 4-1BBL, and HVEM, in tumor progression." (PMID 36358792, 2022). "Early clinical trials so far, however, report modest anti‐tumour effects by targeting CD40133 and downright disappointing results for CD47‐targeting agents." (PMID 35261190, 2022). "Currently, more immune checkpoints are being elaborated upon in tumor studies, such as the B7 family, T cell immunoglobulin, and mucin domain-containing protein 3 (TIM-3), CD47, and CD74." (PMID 35740577, 2022). "In consistent, the present study reveals the anti-CD47 antibody is indeed able to penetrate BBB and bind to tumor cells in irradiated orthotopic GL261 tumors treated with anti-CD47 antibody or combined with FAO inhibitor." (PMID 35314680, 2022). "Although co‐administration of CDDP with anti‐CD47 (CDDP and aCD47) showed a significant antitumor effect, CaCE had an even more dramatic anticancer effect in survival rate and tumor weight." (PMID 36054073, 2022). "Here, we identified a previously unreported therapeutic strategy to reduce CD47 expression by LAT2 inhibition and underscore the potential of LAT2 small-molecular inhibitors, such as BCH, in elimination of CD47-mediated tumor evasion." (PMID 36274066, 2022). "In this study, based on the available information regarding the tumor-immune microenvironment in TNBC and the over-expression of the well-characterized immune checkpoints PD-L1 and CD47, we reconstructed the molecular frame of prototype IAB." (PMID 36009390, 2022). "When the CD47-SIRPα axis was blocked by an anti-human SIRPα antibody, KWAR23, not only macrophages but also neutrophils infiltrated the tumor in a human Burkitt’s lymphoma xenograft." (PMID 35865547, 2022). "Daratumumab in combination with the Fc-silent CD47 blocking antibody hu5F9-IgG2σ achieved statistically significantly increases in phagocytosis of T-ALL cell lines and primary tumor cells compared to CD38 antibodies alone." (PMID 36052078, 2022). "Low pH at the tumor site broke the benzoic imine bond of M1 Exo-Ab, releasing aCD47 and aSIRP, which then inhibited the receptors SIRP on macrophages and CD47 on tumor cells, eradicating the “don’t eat me” signal and improving macrophage phagocytic activity." (PMID 36460660, 2022).
tumor (continued). "Another study also found that Bifidobacterium colonized in the tumor microenvironment can effectively stimulate STING signaling and increase cross-priming of DCs after anti-CD47 treatment." (PMID 36003378, 2022). "Intriguingly, CAFap presented significantly more interactions with tumor-infiltrating T-cell clusters than CAFmyo (p = 0.002), with a similar interactive pattern as that of TAM (e.g., LGALS9_HAVCR2/SORL1/CD47)." (PMID 36333338, 2022). "In primary liver cancer, PROM1+ and CD47+ cancer stem cell (CSC), which was scattered in tumor areas, was found to be gradually increased from leading-edge to tumor to portal vein tumor thrombus, and closely related to TME remodeling and tumor metastasis." (PMID 36313703, 2022). "Additionally, Escherichia coli stably transformed with a plasmid constitutively expressing nanobody antagonist against CD47 could stimulate systemic tumor antigen-specific immune responses, and induced durable tumor regression and long-term survival in a syngeneic tumor model." (PMID 36276157, 2022). "Because cell lines do not reflect the clinical heterogeneity of patients, the dual checkpoint blockade of CD47 and LILRB1 was investigated using tumor cells from patients." (PMID 36389667, 2022). "Utilizing this system to directly knock out the CD47 gene can not only promote the phagocytosis of macrophages but also increase the efficacy of BNCT treatment, so as to reduce the recurrence rate of tumor from two aspects." (PMID 35246144, 2022). "In the future, CD47-based optical molecular imaging could help surgeons make initial judgments about whether tumor tissue in fresh specimens has positive surgical margins or even be used for fluorescence-guided surgery to improve the thoroughness of tumor resection." (PMID 35295998, 2022). "It has been shown that blockade of CD47 facilitated the activation of NADPH oxidase NOX2 in DCs, which in turn prevented phagosomal acidification and decreased the degradation of tumor mitochondrial DNA (mtDNA) in DCs." (PMID 35784290, 2022). "Proximity Ligation Assays (PLA) indicate that CXCR4 and CD47 physically interact on the surface of tumor cells; the binding of CXCL12 to CXCR4 leads to the co-internalization of the CXCR4-CD47 complexes, and therefore to the decrease of surface CD47." (PMID 35565443, 2022). "However, we hypothesize that in the tumor periphery, upregulation of CD47 in TIICs could be a mechanism to protect newly recruited leukocytes from macrophage-mediated phagocytosis, while also allowing the removal of old or exhausted leukocytes in the tumor center." (PMID 36171566, 2022). "DSP107 binds CD47 and 4-1BB, a costimulatory receptor upregulated upon TCR/MHC interaction to stimulate tumor-reactive T cells." (PMID 36429020, 2022). "To compare the effect of exosome delivery of CDDP and aCD47 with the combined administration of CDDP and anti‐CD47 (CDDP&aCD47) on tumor formation, we monitored survival rate up to 60 days measured body weight tumor weight in LLC tumor‐bearing mouse model." (PMID 36054073, 2022). "CD47 CAR helped CAR-T cells engage with CD47+ cells, thereby increasing the possibility of TAG-72 CAR to bind tumor cells with even lower TAG-72-expressing levels." (PMID 36059451, 2022). "Blocking PD-L1 and CD47 on CTCs increases the production of PD1+ B-cells while blocking CD47 on CTCs promotes phagocytosis by macrophages and stimulation of tumour-specific cytotoxic T cells." (PMID 35406441, 2022). "By blocking the CD47/SIRPα axis, SIRPαD1-Fc selectively targets NSCLC cells and activated macrophages to recognize and phagocytose tumor cells." (PMID 36300110, 2022). "Particularly, ICD induced by a TSP1-derived CD47 agonist (PKHB1 peptide: KRFYVVMWKK), and DC activation using TCLs obtained from PKHB1-treated L5178YR tumor cells (PKHB1-TCL), has been reported." (PMID 35890254, 2022).
tumor (continued). "The authors used a combination therapy of CD47-blocking antibodies and CPMV nanoparticles to act synergistically and elicit an anti-tumor immune response." (PMID 34976959, 2021). "In cancer, CD47 null mice had elevated VEGF and VEGFR2 expression and there was increased angiogenesis and accelerated tumor progression in a syngeneic murine model of prostate cancer." (PMID 33869231, 2021). "Factors including gender, age, tumor size, histological grade, tumor location, TNM stage, ARID1A status, and CD47 expression were taken into multivariate survival analysis." (PMID 34805154, 2021). "Since, we saw development of humanized antibodies, next generations anti-CD20, mAbs targeting other markers on tumor cells (CD19 and CD22), its microenvironment (PD-1, CD47), antibody drug conjugates and bispecific T cell engagers." (PMID 34765437, 2021). "Anti-CD47 treatment has shown to play an important role in enhancing macrophage phagocytosis of GBM and promoting an anti-tumor phenotype." (PMID 34041034, 2021). "This agent targets CD47 on tumors and CD40 on antigen presenting cells to enhance antigen presentation to T cells and to induce tumor cell killing." (PMID 33805268, 2021). "The effects of targeting CD47 and PD-L1 were investigated through syngeneic triple-negative breast cancer (TNBC) murine models and tumor organoid platforms." (PMID 34078406, 2021). "Like CD47, MHC-I is expressed ubiquitously, resulting in a need for tumor targeting to prevent unwanted adverse effects." (PMID 33748077, 2021). "Though clinical data on the treatment efficiency of repolarizing agents is limited, it is clear that CD47-SIRPα, CD40/CD40L, and CSF-1/CSF-1R molecular pathways are involved in tumor survival and progression." (PMID 34988021, 2021). "Aiming at the immune regulatory CD47, IMM01 can activate macrophages to phagocytose tumor cells and to present tumor antigens to T cells." (PMID 34717705, 2021). "Double antibody blocking CD47 and HER2 not only inhibited tumor clone formation, but also enhanced macrophage-mediated attack." (PMID 34717710, 2021). "In GBM, preclinical data indicate that blocking the CD47-SIRPα axis can induce antitumor effects, although a combination with chemotherapy may be required to activate ER stress responses that promote tumor cell phagocytosis by professional antigen presenting cells." (PMID 34917090, 2021). "In addition to CD47/SIRPα blockade, bispecific agents currently under investigation were designed to target either another cancer specific cell surface molecule concurrently expressed on the target tumor cells (i.e., CD19, CD20, PD-L1) or a cell surface molecule expressed by T cells (i.e., PD-1)." (PMID 34944850, 2021). "Although the effect of azelnidipine for dual blocking of CD47/SIRPα and TIGIT/PVR interactions indeed occurs within one single model, it is hard to distinguish the contribution to the anti-tumor effects of either single blockade." (PMID 34068552, 2021). "Tumor cells isolated from HTM (black histogram) showed similar expression profiles of cMET and CD24 and slightly different HER2 and CD47 patterns compared to cell culture cells (grey histogram)." (PMID 34070094, 2021). "Upon CD47 blockade treatment, which mitigates the NOX2-mediated reduction of tumor mtDNA degradation, DCs can restore cross-presentation of tumor antigens." (PMID 34290401, 2021). "Further, CD47, a cell transmembrane protein expressed in ESCC tumor cells, can inhibit CD8+ T-cell infiltration and anti-tumor immune responses in a DC-dependent manner, by interacting with signal regulatory protein-α (SIRPα), expressed in DCs." (PMID 33995371, 2021). "Inhibition of the CD47-SIRP-alpha axis in combination with autophagy inhibitors increased macrophage infiltration, tumor cell apoptosis, and median survival in mouse models of GBM." (PMID 34041034, 2021).
tumor (continued). "Inhibitors of CSF1R, CCL2 and CCR2, CD47/SIRPα complex antagonists, CD40 agonist antibodies, and inhibitors of PI3Kγ and TREM2 protein are undergoing clinical evaluation for various tumor types." (PMID 34638378, 2021). "CD47-dependent antagonism of NO signaling by TSP1 limits the perfusion of healthy tissues, but this signaling is impaired in the tumor vasculature." (PMID 33925464, 2021). "This new set of data challenges the current “CD47 dogma” according to which most CD47 inhibitory effects on anti-tumor immunity rely on SIRPα binding, and considerably increase the relevance of inhibiting TSP-1/CD47 axis in cancer therapy." (PMID 34638503, 2021). "Given the possible enhancement of tumor immunity, combinations of HDAC inhibitors and CD47 targeting therapies are underway." (PMID 34944850, 2021). "Knockout of SIRP-α prevented CD47:SIRP-α interactions between cancer cells and macrophages, and increased the phagocytosis of tumor cells by macrophages 4-fold." (PMID 34683963, 2021). "Mechanisms through which CTCs can escape from immune cells include the expression of PD-L1 and CD47 and the alteration of FAS/FASL, which can promote T cell apoptosis or protect tumor cells from apoptosis." (PMID 34830787, 2021). "Various cytokines, such as IL-13, IL-15, and IL-32, and surface proteins, including CD47, CD40, and CD28, provide the direct molecular bridge between tumor cells and adjacent cells, resulting in tumor progression." (PMID 34830466, 2021). "By contrast, the number of tumor-infiltrating CD68+M, CD163+M2, and CD47 cells was higher, and these cells were significantly associated with decreased OS." (PMID 34439378, 2021). "In contrast, induction of CD47 on tumor cells, a prominent “don’t-eat-me” signal, by IFN-γ relied on the JAK1–STAT1–IRF1 axis, which prevented phagocytosis of stressed tumor cells by macrophages." (PMID 34830176, 2021). "In addition, CD47 is highly expressed in tumor cell-derived exosomes, can create a tumor microenvironment, lay the foundation for tumor metastasis, migration and invasion, and enable tumor cells to escape T cells and NK nuclear macrophages, thus promoting the occurrence and development of tumors." (PMID 33828985, 2021). "Here, we examined the over-expression of CD47 and PVR in a broad spectrum of cancers and tumor cell lines." (PMID 34068552, 2021). "MYC has also been shown to regulate anti-tumor immune responses through various mechanisms, such as secretion of CCL9 and IL-23, and expression of PD-L1 and CD47." (PMID 34947972, 2021). "We further investigated the anti-tumor effects of azelnidipine in a CT26 model, which is widely used for CD47/SIRPα and TIGIT/PVR blockade therapy and the exploration of the T cell immune response." (PMID 34068552, 2021). "Blocking PD-1 can reduce the expression of CD47 in TME to restore T cell activity 112, or partially activate DC by TME co-stimulatory molecules to promote an effective anti-tumor T cell response." (PMID 33391402, 2021). "Meanwhile, we also analyzed the expression of CD47 and PVR on CT26 tumor cells derived from the tumor tissues." (PMID 34068552, 2021). "In the case of TSP-1, as mentioned in introduction, majority of available literature indicate the role of tumor microenvironment, especially TSP-1/CD47 interaction seems to play key role." (PMID 34501309, 2021). "Here, we analyzed the expression of CD47 and PVR from the GEO database and tested the existence on the tumor cell lines by flow cytometry." (PMID 34068552, 2021). "This bsAb is designed by combining a low-affinity CD47 targeting antibody with a high-affinity antibody against CD19, to make sure that CD47 is employed by the bsAb only on tumor cells that co-expressed both antigens." (PMID 34305918, 2021). "Here, 3D in vitro tumor models, an in vivo mouse model, and molecular dynamics simulations are used to investigate the effect of NTP on CD47, a key innate immune checkpoint." (PMID 33540720, 2021).
tumor (continued). "In our study, we analyzed the presence of immunosuppressive molecules: PD-L1, CD47, CD73, Fas and FasL on tumor cells and CSCs in LN aspirates and referred it to the lymphocyte subpopulation in peripheral blood." (PMID 34203877, 2021). "It has been reported that CD47 bind to SIRP-a on macrophage, which is an important mechanism in intervening the capacity of macrophage phagocytosis in irradiated tumor microenvironment." (PMID 33867819, 2021). "In the present study, 269 advanced CRC lesions were immunohistochemically evaluated for CD47, SIRPA, CD68, and CD163 expression in tumor cells and TAIs." (PMID 33799989, 2021). "The CD47/SIRPα and TIGIT/PVR signaling pathway jointly contribute to the immunosuppressive tumor microenvironment." (PMID 34068552, 2021). "Antibodies for CD47 (Hu5F9-G4) and SIRP1α (CC-95251 and 1H9), as well as SIRP1αFc fusion protein (TTI-621), promote phagocytosis, reducing tumor burden in numerous animal models, and are being tested in a clinical trial." (PMID 33919979, 2021). "The constructed anti-CD47 ADC effectively targeted TNBC cells and tumors, released potent drugs intracellularly, and significantly inhibited the tumor growth post GC treatment in a xenograft model with minimal side effects." (PMID 34452008, 2021). "The anti-CD47 secretion anti-PD-L1 CAR-T cells display better effects on the tumor sizes and mice survival than that of anti-PD-L1 CAR-T cells plus the systematic administration of anti-CD47 and anti-PD-L1 CAR-T-only groups." (PMID 33567640, 2021). "Here, an elevated expression of CD47 and PVR was observed in tumor tissues and cell lines analyzed with the GEO datasets and by flow cytometry, respectively." (PMID 34068552, 2021). "After incomplete removal of tumor tissues by surgery, the mice were i.v. injected with three doses of phosphate buffered saline (PBS), P-NVs, M1-NVs, SαV-C-NVs, CD47 mAbs or hNVs every other day." (PMID 32999291, 2020). "Therefore, CD47 neutralizing antibodies could improve tumor lysis by effector cells." (PMID 32457743, 2020). "We next assessed the biological function of CD47/CD20 BsAb including phagocytosis and anti-tumor activity." (PMID 31931812, 2020). "Targeting both CD47 and autophagy in NSCLC xenograft models elicited enhanced anti-tumor effects, with the recruitment of macrophages, activated caspase-3, and overproduction of ROS at the tumor site." (PMID 32746880, 2020). "CD47, a member of the immunoglobulin superfamily, is known to play an antiphagocytic role in the TME and to contribute with tumor recurrence." (PMID 32824974, 2020). "Consistent with the in vitro results, overexpression of CD47 increased tumor growth in DLD1 cells compared to control cells, while knockdown of CD47 inhibited tumor cell growth in SW480 cells." (PMID 32226539, 2020). "Agents blocking CD47–SIRP1α interaction (e.g., TTI-621) promotes macrophage-mediated phagocytosis of cancer cells and T cell activation, thus reducing tumor growth." (PMID 32823961, 2020). "Evaluation of adaptive immune cell profiles in the setting of combined TMZ and anti-CD47 treatment demonstrated a significant increase in both CD4+ and CD8+ T cells within the tumor." (PMID 32198351, 2020). "To further improve the preference of antibodies binding to tumor cells, we constructed anti-CD47/CD20 BsAb consisted of HuNb1 and Rituximab, showing stronger anti-tumor activity in vivo compared to HuNb1 and Rituximab." (PMID 31931812, 2020). "Collectively, these findings indicate that by promoting tumor cell phagocytosis, combined TMZ and anti-CD47 treatment enhance the cross priming of antigen-specific CD8+ T cells by APCs." (PMID 32198351, 2020). "Recent studies have shown that blocking CD47 can inhibit VEGF and enhance antiangiogenesis in NSCLC by enhancing macrophage infiltration and tumor cell destruction." (PMID 32733941, 2020). "In human cell lines, the BsAb showed selective binding to tumor cells with dual expression of CD20 and CD47." (PMID 32677994, 2020).